IFNG (interferon gamma)
Diseases named in the same sentence as IFNG in open-access papers (continued):
Sharing a sentence is not in itself a finding about the gene and the disease.
melanoma (continued). "We demonstrate that loss of tumor MBNL expression results in an attenuated response to interferon gamma and reduced tumor antigen presentation in melanoma, breast cancer, and colorectal cancer cells." (PMID 40305509, 2025). "Given that melanoma resistance to NK‐cell cytotoxicity is mediated by IFNγ, we examined the IFNγ role in regulating MHC II expression on melanoma cells during co‐culture with NK‐cells." (PMID 41078003, 2025). "IFNγ signals were exclusively derived from NK‐cells and CD8+ T lymphocytes, whereas CRTAM signals were linked to both NK‐cells and melanoma cells." (PMID 41078003, 2025). "In summary, we identified and validated genes that are controlled by IFNγ in melanoma cells and are involved in regulating their sensitivity to NK‐cell‐mediated cytotoxicity." (PMID 41078003, 2025). "Next, we focused on understanding the molecular details of IFNγ‐mediated melanoma cell resistance formation." (PMID 41078003, 2025). "Since IFNγ induces both the expression of immunostimulatory and immunosuppressive genes, we set out to investigate the potential effect of melanoma dedifferentiation on IFNγ-induced gene expression, particularly on immune related genes." (PMID 39736644, 2024). "We incubated B16-F10 mouse melanoma cells with IFNγ overnight to induce intracellular signaling, which is known to be critical to the function and phenotype of cancer cells." (PMID 38636457, 2024). "Interferon-gamma signaling has been identified as an important mechanism for the upregulation of PD-L1 on melanoma cells and escape from immune recognition." (PMID 38386085, 2024). "To validate that Mi-2β-regulated immune response is based on the enhanced IFNγ-signaling, we detected CXCR3 in the TME of Mi-2β-deficient melanomas by IHC with a specific anti-CXCR3 antibody." (PMID 38461299, 2024). "Previous studies have demonstrated that IFNγ-induced PD-L1 expression is reliant on JAK1/JAK2 activity, and that PD-L1 promoter activity and subsequent expression is mainly influenced by STAT1/STAT3 and IRF1 in IFNγ treated melanoma cells." (PMID 39736644, 2024). "To explain the molecular context of high PD-L1 expression in the dedifferentiated melanoma cells, we divided the MITFlow group into PD-L1high and PD-L1low based on their IFNγ-induced PD-L1 expression and then compared those two groups." (PMID 39736644, 2024). "Mechanistically, we find inhibition of Notch1 increases CD8+ T cell degranulation and IFNγ and Granzyme B production both in vitro and in vivo, leading to melanoma cell killing." (PMID 39491031, 2024). "Dedifferentiation and IFNγ stimulation can each exert contrasting effects on melanoma progression based on the cellular and/or therapeutic context." (PMID 39736644, 2024). "In summary, our results show that melanoma dedifferentiation influences IFNγ signaling in a context-dependent manner." (PMID 39736644, 2024). "The heatmap displayed that melanomas with high IRE1α activity have increased expressions of TIL signature molecules like IFNG, GZMB, CD8A and CXCL10." (PMID 38291473, 2024). "Analysis of IFNγ levels in the supernatant of IL-2-expanded effector OT-I CD8 cells (two expansions) co-cultured with B16-OVA melanoma cells showed higher levels of IFNγ by MCJ OK OT-I CD8 cells than WT OT-I cells." (PMID 38789421, 2024). "In this study, lncRNA GRASLND seems to have a direct impact on melanoma antigen presentation by inhibiting IFNγ signaling and thus impairs the enhancement of the antigen presentation by IFNγ." (PMID 39398277, 2024). "Based on this and our RNA-Seq results on the IFNγ-associated gene sets, we suspected a suppressor role of GRASLND on IFNγ signaling in melanoma cells." (PMID 39398277, 2024).
melanoma (continued). "In contrast, murine models of melanoma treated primarily with IT followed by TT produced a prolonged tumor regression due to the accumulation of proinflammatory M1 macrophages, interferon Gamma secretion, and an increase in CD8 T lymphocytes." (PMID 38450188, 2024). "Plasmablast-like TIL-Bs from patients with ovarian cancer and melanoma show elevated levels of transcripts for IFNγ and chemokines like CCL3, CCL4, and CCL5, which attract T cells, macrophages, and NK cells, leading to increased T cell infiltration." (PMID 39068459, 2024). "In contrast, the number of activated CD8+IFNγ+ TC cells was higher in B16 melanomas from Foxp3GFP-Fth∆/∆ vs. control Foxp3GFP mice (Fig. EV5F)." (PMID 38499786, 2024). "Altogether, our results suggest that HDAC6 plays a role in regulating CD47 expression in melanoma cells and that HDAC6i can prevent IFNγ-driven upregulation of CD47." (PMID 38414061, 2024). "The frequency and number of activated CD4+IFNγ+ TH cells isolated from B16 melanomas was similar in Foxp3GFP-Fth∆/∆ vs. control Foxp3GFP mice (Fig. EV5F)." (PMID 38499786, 2024). "In the keratinocyte- and melanoma-derived melanosome overlaps, we observed significant enrichment for pathways related to the positive regulation of the IFNγ, IL-1, T-helper 2, and type I interferons pathways indicative of pro-inflammatory signaling." (PMID 38719996, 2024). "IFN gamma (IFNγ) activated dermal tumor lymphatic endothelial cells inhibit cytotoxic T cells accumulation in melanoma." (PMID 39325128, 2024). "It has a dual role in melanoma progression where conserved IFNγ signaling is essential for response to immune checkpoint inhibitor (ICI) therapies, whilst it can also confer increased metastatic potential and promote multigenic ICI resistance." (PMID 39736644, 2024). "miR-146a has a key role in the STAT1/IFNγ axis within the melanoma microenvironment, influencing melanoma cell migration, proliferation, mitochondrial function, and PD-L1 expression." (PMID 38462628, 2024). "Tumour necrosis factor-alpha (TNFα), interleukin-2 (IL-2), and interferon-gamma (IFNγ) are shown to be critical in fighting melanoma cells." (PMID 38334660, 2024). "In this study, we investigated how the differentiation status of melanoma cells affects their response to IFNγ." (PMID 39736644, 2024). "Our findings demonstrate that in differentiated melanomas elevated expression of GRASLND interferes with anti-tumor effects of IFNγ, suggesting a role of GRASLND in tumor immune evasion." (PMID 39398277, 2024). "Despite lncRNA’s tissue- and cell type-specificity, we found an immune-relevant role of GRASLND in suppressing the IFNγ signaling in melanoma, and thus influencing the HLA-I-APM." (PMID 39398277, 2024). "Analysis of the GSE154996 data set suggests that dedifferentiated melanoma cells actually show altered responses to IFNγ, characterized by enhanced inflammatory signaling." (PMID 39736644, 2024). "Inhibition of the JAK kinases, NF-κB and STAT3 with small molecule inhibitors, and siRNA mediated knockdown of STAT1 and IRF1 was applied to investigate the molecular mechanism behind IFNγ induced PD-L1 expression in dedifferentiated melanoma cells." (PMID 39736644, 2024). "In mouse models of ovarian cancer and melanoma, CD8+ T cells alter lipid metabolism in tumors by releasing interferon γ (IFNγ, encoded by IFNG)." (PMID 39284708, 2024). "Lastly, dedifferentiated patient derived melanoma cell lines showed enhanced inflammatory signaling in response to IFNγ compared to differentiated cells, and tended to have higher PD-L1 expression, associated with increased IRF1 expression and activity." (PMID 39736644, 2024).
melanoma (continued). "In this study, the authors demonstrated that restoring tryptophan with IDO1 inhibitors in a TRP-deprived milieu protected melanoma cells from being eliminated by T cells by recovering general protein synthesis triggered by IFNγ-induced tryptophan deprivation." (PMID 38273337, 2024). "Dedifferentiated melanoma cells have been reported to display enhanced responses to IFNγ stimulation when compared to differentiated melanoma cells." (PMID 39736644, 2024). "But in Th1 abundant environment, IFNγ reprofiles the cytokine expression of Th17, leading to strong tumor elimination capacity in B16 melanoma." (PMID 38827732, 2024). "IFNγ produced by rNDV-infected melanoma showed induction of Th1 cytokines in co-cultured lymphocytes and IFNγ was also induced by rNDV-GFP." (PMID 37022566, 2023). "In depth transcriptomic and immune-metabolic profiling was applied to analyze maturation states of melanoma patient-derived IFNγ + LPS matured DC (mDC) used for the autologous vaccine preparation." (PMID 37938561, 2023). "According to the report, NK cells that underwent differentiation increased cytotoxicity towards melanoma targets by exhibited heightened production of IFNγ." (PMID 37620327, 2023). "In these HLA-A2:01+ melanoma cell lines, Melan-A peptide presentation induced a small but significant increase in the fraction of activated (IFNγ+CD107+) allogeneic HLA-A02 matched or autologous CD8+ T cells." (PMID 36934113, 2023). "Increased T cell infiltration and interferon gamma (IFNγ) pathway activation are seen in tumors of melanoma patients who respond to ICI (immune checkpoint inhibitor) or MAPK pathway inhibitor (MAPKi) therapies." (PMID 37435085, 2023). "We also demonstrated that IFNγ-inducible NAMPT in melanoma cells counteracts the growth-suppressive effects of IFNγ." (PMID 36900204, 2023). "Altogether, these data indicate that the inhibition of IFNγ-induced NAMPT leads to cell death in melanoma." (PMID 36900204, 2023). "We provide evidence that melanoma cells directly respond to IFNγ-activated STAT1 by increasing Nampt, which improves their fitness during tumor immunity." (PMID 36900204, 2023). "To validate these findings in a more clinically relevant setting, we treated a panel of PDX melanoma cell lines with IFNγ and again observed intrinsic differences in their susceptibility to it." (PMID 36812891, 2023). "To do so, we treated B16-F10 melanoma cells with IFNγ, FK866, or a combination of the two and analyzed our data using flow cytometry to quantify live and dead cell populations." (PMID 36900204, 2023). "The dedifferentiation subtype of melanomas cells is promoted by IFNγ in response to ferroptosis inducers." (PMID 37182170, 2023). "The expression of oncolytic and apoptosis-related genes, the immune response by lymphocytes, and IFNγ expression were evaluated in virus-infected melanoma cells." (PMID 37022566, 2023). "In one example, an attenuated S. typhimurium expressing recombinant interferon-gamma (IFN-γ) successfully invaded melanoma cells and induced cytotoxicity in melanoma-bearing mice, while showing minimal toxicity to normal cells." (PMID 38065982, 2023). "We show here that IDO1 inhibition leads to an adverse protection of melanoma cells to T cell-derived interferon-gamma (IFNγ)." (PMID 36812891, 2023). "We treated YUMM 1.1, 3.2, and 5.2 mouse melanoma cell lines and A375 and A2058 human melanoma cells with IFNγ." (PMID 36900204, 2023). "CD271 can be induced by IFNγ, which is produced in high volumes by NK cells, thus contributing to immune escape by driving the downregulation of melanoma antigens." (PMID 38067178, 2023). "In our cohort, IFNγ signaling was disrupted in only 1/22 PD1 PROG melanoma, and this JAK2-mutant progressing tumor was also de-differentiated." (PMID 36934113, 2023). "We show that IFNγ signaling upregulates NAMPT in melanoma cells, increasing cell proliferation and survival." (PMID 36900204, 2023).
melanoma (continued). "IFNγ and FK866 combination treatment significantly decreased melanoma growth, but we wanted to assess the contribution of IFNγ-inducible NAMPT in melanoma growth, specifically." (PMID 36900204, 2023). "Activation of TLR1/2 promotes the effector activity of CD8+ T cells in B16 melanoma cells both in vivo and in vitro through upregulation of perforin, Granzyme B, IFNγ and TNF-α." (PMID 37936697, 2023). "The expression of canine IFNγ was examined by western blotting in rNDV-cIFNγ-infected melanoma cells, using anti-canine IFNγ antibodies." (PMID 37022566, 2023). "The excessive activation of IFNγ leads to the upregulation of immune checkpoints and dedifferentiation of melanoma cells." (PMID 37174106, 2023). "We selected an IFNγ-responsive human melanoma cell line (D10), which showed a steep decline in TRP levels upon T cell and IFNγ co-culture." (PMID 36812891, 2023). "For instance, TILs dramatically upregulate the expression of PDL1 in melanoma cells by secreting high amounts of cytokines, such as IFNγ, which results in the suppression of TILs." (PMID 39282109, 2023). "The inhibition of ULK1 substantially reduces IFNγ-induced PD-L1 and PD-L2 expression in melanoma cells." (PMID 38067169, 2023). "discover an adverse effect of IDO1 inhibition: protecting melanoma cells from the effects of T cell-derived IFNγ." (PMID 36812891, 2023). "We performed chemical genomics and whole genome targeting CRISPR/Cas9 screens using patient-derived melanoma lines to uncover essential nodes in the IFNγ-mediated growth inhibition pathway." (PMID 37803324, 2023). "Our study demonstrates a novel cell death pathway mediated by the IFNγ-ERK signaling axis in melanoma cells." (PMID 37803324, 2023). "Upregulated ULK1 in melanoma cells is positively correlated with the IFNγ-induced expression of immunosuppressive genes, such as PD-L1 and PD-L2." (PMID 38067169, 2023). "Deletion of protein tyrosine phosphatase non-receptor type 2 (Ptpn2), a regulator of growth factor and cytokine signaling pathways, has been shown to sensitize murine B16F10 melanoma cells to IFNγ and anti-PD-1 immunotherapy." (PMID 36968224, 2023). "In mouse melanoma and fibrosarcoma models, pharmacological inhibition or genetic deficiency of A2AR increases CD8+ T cell tumor infiltration and IFNg production, and reduces tumor growth." (PMID 37842241, 2023). "Recent studies have revealed that IL7 plays a significant role in glioma, melanoma and leukemia by contributing to anti-tumor effects through the release of cytokines, including IFNG, IL1A, IL1B, TNF, IL2 and IL4." (PMID 37958451, 2023). "We used a panel of 31 patient-derived melanoma lines to determine the extent of growth inhibition upon continued exposure to IFNγ." (PMID 37803324, 2023). "Melanoma cells also exhibited a significant decrease in cell confluency when treated with IFNγ and FK866, and we sought to identify if it was due to cell death or an inhibition of proliferation." (PMID 36900204, 2023). "Despite clear evidence for the involvement of ERK, the mechanism of crosstalk between ERK and IFNγ signaling and how it leads to the induction of stress response in melanoma cells remains to be elucidated." (PMID 37803324, 2023). "HLA-E is typically expressed at negligible levels in melanoma cells, but surface expression of HLA-E can become drastically upregulated in the presence of IFNγ, which is produced in high quantities by NK cells." (PMID 38067178, 2023). "Taken together, our results indicate the presence of separate IFNγ-mediated cell death and cell cycle arrest pathways in melanoma cells." (PMID 37803324, 2023). "In vitro, methionine supplementation increased CD8+ T cell survival and IFNg and TNFa production, while inhibiting murine melanoma tumor growth." (PMID 37842241, 2023).
melanoma (continued). "In mouse melanoma models, lactic acid was also shown to diminish interferon-gamma (IFN-γ) production in T cells, and increased lactate dehydrogenase expression was negatively correlated with T-cell activation." (PMID 37180129, 2023). "We examined the effect of the PTPN2 inhibitors on the IFNγ signaling response of mouse melanoma and colon cancer cell lines in vitro by comparing the effectiveness of the PTPN2 inhibitors with results of CRISPR/Cas9-mediated Ptpn2 deletion." (PMID 36968224, 2023). "Other MS immunopeptidome analysis of breast, lung, ovarian cancer, and melanoma cell lines that were treated with IFNγ showed similar remodeling with a large proportion of peptides presented in only untreated or IFNγ-treated cells." (PMID 37991387, 2023). "In contrast, the two extracts decreased IL-10 levels in the B16-F10 murine melanoma model, but only P2Et treatment increased TNFα and IFNγ levels, indicating increased activation of the effector immune response." (PMID 38069022, 2023). "In analyzing the clinical trial results, ex vivo ELISPOT assays were performed to detect IFNγ-producing CD8 and CD4 T-cell responses specific to the DC vaccine loaded melanoma-associated antigens Tyrosinase, MART-1 and MAGE-A6." (PMID 37938561, 2023). "We constructed a recombinant Newcastle disease virus (rNDV) that promotes the extracellular release of IFNγ from the virus-infected melanoma." (PMID 37022566, 2023). "We therefore incorporated IFNγ DNAinto NP formulations to modulate the MHC-I expression in MCC cellsand melanoma tumors." (PMID 37797944, 2023). "Transcriptome analysis in nivolumab-treated melanoma patients showed the benefits of increasing IFNγ and decreasing SLC3A2 expression, which improved patient survival." (PMID 37996827, 2023). "has reported that host Gpr68-deficiency led to increased effector CD8+ T cell number and enhanced T cell proliferation, migration as well as IFNγ, TNFα and GramB production, which is responsible for the impaired melanoma tumor growth in male mice." (PMID 37350933, 2023). "We treated B16-F10 mouse melanoma cells with IFNγ for 6 or 24 h, which significantly increased NAMPT mRNA expression." (PMID 36900204, 2023). "Another study has shown that cytokines secreted by T cells such as TNF-α and IFNγ in melanoma cell culture medium induced dedifferentiation and increased ferroptosis in the cells through activating of NF-κB or STAT1 signaling pathways." (PMID 37996827, 2023). "We propose a model in which IFNγ signaling leads to the hyperactivation of ERK in melanoma cells, leading to cell death." (PMID 37803324, 2023). "Together, these results demonstrate that the intrinsic sensitivity of melanoma cells to IFNγ, T cells, and PD-1 blockade correlates with their ability to show a dynamic MITF response." (PMID 36812891, 2023). "This method increased CD8+ T cell infiltration and production of granzyme B and IFNg, reduced intratumoral adenosine and Treg populations, and synergized with anti-PD-1 treatment in mouse melanoma models." (PMID 37842241, 2023). "For instance, reduced interferon-gamma (IFNγ) production is often observed in the tumor-infiltrating lymphocytes (TILs) of patients with different forms of cancer, including melanoma, HNSCC, and ovarian cancer." (PMID 37239368, 2023). "first showed that ferroptosis-inducing agents are sensitive to reduced dedifferentiated melanoma cells after induction of Interferon Gamma (IFNγ)." (PMID 37182170, 2023). "Next, mice were inoculated with the IFNγ-stimulated or unstimulated B16 melanoma cells, followed by anti–PD-1 or anti–PD-L1 treatment." (PMID 36546872, 2023). "We demonstrate that interferon gamma (IFNγ) mediates the metabolic reprogramming of melanoma cells by inducing the essential NAD+ salvage pathway enzyme nicotinamide phosphoribosyltransferase (NAMPT) gene through STAT1 binding to the NAMPT locus." (PMID 36900204, 2023).